APOE (apolipoprotein E)
Diseases named in the same sentence as APOE in open-access papers (continued):
Sharing a sentence is not in itself a finding about the gene and the disease.
Alzheimer disease (continued). "The dysregulation of Apolipoprotein E can disturb cholesterol homeostasis, resulting in several diseases, including cardiovascular disease and Alzheimer’s disease." (PMID 38161428, 2023). "Among APOE‐ε4 non‐carriers, patients with Alzheimer's disease in the highest PRS quintile had 4.1 years younger age of onset of disease (p = 0.0002) compared to patients in bottom quintiles, but only 0.43 years in APOE‐ε4 carriers." (PMID 36946865, 2023). "The APOE genotypes-inflammation interaction have been reported in multiple other conditions, such as postoperative delirium, longevity and Alzheimer’s disease." (PMID 36640294, 2023). "ApoC-III as well as the other members of the apolipoprotein C family (ApoC-I and ApoC-II) interact with ApoE and influence the pathophysiology of Alzheimer’s disease (AD)." (PMID 36689070, 2023). "GWAS for several diseases have led to the identification of a large number of associated variants in functionally plausible genes as in the case of FTO for obesity, SLC30A8 for type 2 diabetes, and APOE for Alzheimer’s disease." (PMID 38254924, 2023). "A previous meta‐analysis of 27 independent studies, with data representative of non‐Hispanic White individuals in North America and Europe, found that the effect of a single copy of APOE ε4 on Alzheimer's disease (AD) was similar for women and men." (PMID 36790027, 2023). "Data from the Alzheimer's Disease Neuroimaging Initiative (ADNI) cohort also showed that plasma biomarker profiles differed across APOE genotype carrier groups in patients with AD dementia, mild cognitive impairment, and cognitively normal participants." (PMID 37584418, 2023). "Thus, the possible post-COVID-19 cognitive decline and the relationship between the APOE polymorphism and post-COVID-19 severe and cognitive conditions raise concerns regarding the subsequent development of neurodegenerative diseases, such as Alzheimer’s disease." (PMID 38137059, 2023). "Hackenhaar F.S., Josefsson M., Adolfsson A.N., Landfors M., KauppiK., Hultdin M., Adolfsson R., Degerman S., Pudas S. Short leukocytetelomeres predict 25-year Alzheimer’s disease incidence innon-APOE ε4-carriers." (PMID 37808212, 2023). "Apolipoprotein E (APOE) and apolipoprotein J (APOJ) have been shown to be associated with the development of Alzheimer’s disease." (PMID 37626031, 2023). "BBB permeability was also reported to be related to the E4 variant of apolipoprotein E (APOE4) genotype, which is a known risk factor for Alzheimer’s disease." (PMID 38058998, 2023). "Present studies on the relationship of APOE to the pathogenesis of Alzheimer's disease have involved β-amyloid (Aβ), tau neurofibrillary degeneration, microglia, astrocyte responses and the BBB." (PMID 37008065, 2023). "The mechanisms of incomplete penetrance of risk-modifying impacts of apolipoprotein E (APOE) ε2 and ε4 alleles on Alzheimer’s disease (AD) have not been fully understood." (PMID 35809216, 2023). "Four genes have been identified to be associated with Alzheimer’s disease, namely, the amyloid precursor protein (APP) gene, the presenilin 1 (PSEN1) gene, the presenilin 2 (PSEN2) gene and the apolipoprotein E (ApoE) gene." (PMID 37362440, 2023). "The alleles of the APOE gene regulate DP, CTE and Alzheimer’s dementia in the same way (allele ε2 being “protective,” allele ε4 “predisposing”)." (PMID 36950132, 2023). "The ε4 allele of apolipoprotein E (APOE4) and aging are the major risk factors for Alzheimer’s disease (AD)." (PMID 38275378, 2023). "Apolipoprotein E (ApoE) is a 299-amino acid protein involved in lipid transport and cholesterol homeostasis that plays a key role in Alzheimer’s disease (AD)." (PMID 36749730, 2023). "As previously observed, APOE explains a significant proportion of the known genetic heritability in Alzheimer's disease while the remainder the genome PRS explains only about 7–10%." (PMID 36946865, 2023).
Alzheimer disease (continued). "Article: Pinals RL, Tsai L-H (2022 Sep 27) Building in vitro models of the brain to understand the role of APOE in Alzheimer’s disease." (PMID 36456178, 2023). "For example, the Alzheimer Disease (AD)-associated proteins APP, BACE1, Nicastrin, Tau, APOE and TREM2 all have several N- and O-glycosylations." (PMID 37201132, 2023). "The apolipoprotein E (APOE) gene is a crucial genetic factor that plays a significant role in the risk of developing dementia, primarily Alzheimer's disease." (PMID 38074067, 2023). "Multiple studies have investigated the relationship between ApoE genotype and Alzheimer’s disease progression." (PMID 37693748, 2023). "Apolipoprotein E (APOE)*2 and APOE*4 are, respectively, the strongest protective and risk-increasing, common genetic variants for late-onset Alzheimer disease (AD), making APOE status highly relevant toward clinical trial design and AD research broadly." (PMID 37930705, 2023). "One study demonstrated that, amongst the major alleles of APOE, there is a significant association between APOE4 and the late onset of Alzheimer’s disease, meaning that ApoE4 seeds Aβ plaque more abundantly compared to other ApoE members." (PMID 37513826, 2023). "We used the estimated prevalence of Alzheimer's disease for individuals over age 65 years of 13%30 as a reference to determine the influence of the PRS and APOE genotype on recurrence risk." (PMID 36946865, 2023). "Within the large group of apolipoproteins, apolipoprotein E (ApoE) is one of the most studied members due to its implications in Alzheimer’s disease." (PMID 37339976, 2023). "For instance, APOE has been shown to affect the progression of Alzheimer’s disease through immune regulation." (PMID 37153564, 2023). "Recent single-cell RNA sequencing studies have found that microglia upregulate, whereas astrocytes downregulate the ApoE expression in human brains with Alzheimer’s disease pathology." (PMID 36710921, 2023). "Associations of the APOE-ɛ4 and a higher PRS with CSF biomarker levels reflect neurodegenerative changes that are linked to Alzheimer’s disease." (PMID 37834213, 2023). "CU APOE-ε4 carriers with a positive Aβ PET VR in regions known to accumulate amyloid at later stages of the Alzheimer’s disease (AD) continuum exhibited a steeper cognitive decline." (PMID 36856866, 2023). "The Bax exon 2 splicing had no statistical correlation with the AD patient’s APOE genotypes (apolipoprotein E, especially APOE4, is a well-documented genetic risk factor for Alzheimer’s disease)." (PMID 37371550, 2023). "Apolipoprotein E4 (APOE4) is an important driver of Tau pathology, gliosis, and degeneration in Alzheimer’s disease (AD)." (PMID 37863057, 2023). "Apolipoprotein E (apoE) interaction with amyloid β-protein precursor (APP) has garnered attention as the therapeutic target for Alzheimer’s disease (AD)." (PMID 37211092, 2023). "Gut dysbiosis has been identified as a crucial factor of Alzheimer's disease (AD) development for apolipoprotein E4 (APOE4) carriers." (PMID 37704738, 2023). "The ε4 variant of APOE (APOE4) is the strongest and most common genetic risk factor for Alzheimer's disease (AD)." (PMID 36762973, 2023). "The scientific literature has presented many mechanisms contributing to Alzheimer’s disease (AD), including amyloid-β (Aβ), protein tau, and apolipoprotein E (APOE), as the crucial elements of the AD pathophysiology." (PMID 36982505, 2023). "The APOE region accounts for much of the measurable contribution to Alzheimer’s disease, with smaller polygenic contribution from other measured common genetic influences." (PMID 35169705, 2022). "Metabolism in the Louvain algorithm-derived module containing regions related to Alzheimer’s disease drove the strong correlation between APOE expression and brain metabolism (Module 3)." (PMID 36092303, 2022).
Alzheimer disease (continued). "Previously, we demonstrated that apolipoprotein E mediates sulfatide depletion in animal models of Alzheimer’s disease, and that sulfatide levels in brain tissue from middle-age APOE4-expressing transgenic mice were lower than those found in wild-type mice." (PMID 36613677, 2022). "Previously, sex and apolipoprotein E (APOE) genotype had distinct effects on the cognitive trajectory across the Alzheimer’s disease (AD) continuum." (PMID 35197846, 2022). "The functional implications of the relation between APOE and the 2 pathological hallmarks has been excessively studied and reviewed in the scientific field of Alzheimer’s disease." (PMID 36066633, 2022). "These include APOE, PRKAA1, and MAP3K1, which were previously reported to be associated with Alzheimer’s disease (AD)." (PMID 35580864, 2022). "Stratifying by APOE status, the risk of Alzheimer’s disease was reduced only in individuals with high genetic risk, as indicated by above-median MR– PRS (50% cutoff) or who had at least one APOE ε4 allele." (PMID 37118290, 2022). "Previous studies have highlighted links between a high-glycemic-load (GL) diet and Alzheimer’s disease in apolipoprotein E ε4 (APOE4) carriers." (PMID 35745215, 2022). "In addition, genetically determined Alzheimer’s disease was causally associated with increased risk of hip fractures, and a sensitivity study excluding the genome-wide significant hip fracture SNP rs429358 at the APOE locus revealed a similar causal association." (PMID 36260985, 2022). "One hundred cognitively healthy adults, aged 45–70 years, with different risks for Alzheimer's disease (i.e., ApoE genotype) will be recruited and randomized into either a multi-domain exercise group or an online educational course control group." (PMID 36062144, 2022). "Future studies are needed to better understand the relationships between the overall metabolic status and HDL particle structure and function in the context of Alzheimer’s disease and the APOE genotype." (PMID 35884800, 2022). "Apolipoprotein E (APOE) and clusterin (CLU) involved in cholesterol transport and metabolism, are associated with an increased risk of Alzheimer’s disease (AD), indicating the underlying predictive roles of cholesterol metabolism in cognitive decline." (PMID 35982405, 2022). "Importantly, the ApoE gene is associated with Alzheimer's disease, and is involved in cholesterol transportation in the brain, and the lipids in the brain may then influence the function of the β- and γ-secretase, which are cleavage enzymes involved in Aβ formation and aggregation." (PMID 36247924, 2022). "A recent study showed that a lipid-transporting glycoprotein named apolipoprotein E (ApoE), which is a major protein in Alzheimer’s disease, has the ability to protect cells from various ferroptosis inducers, including erastin and SAS." (PMID 36581640, 2022). "Further, we have shown for the first time that genetic variants that contribute to both Alzheimer’s disease and CAD beyond APOE are a strong predictor of white-matter lesions in the occipital lobe in subjects already diagnosed with Alzheimer’s disease." (PMID 36523268, 2022). "APOE and CD33 expressions were especially high (and SORL1 expression and FDG PET SUVR were especially low) in regions most susceptible to Alzheimer’s disease, such as para-hippocampus and entorhinal cortex." (PMID 36092303, 2022). "LRP1 mediates and regulates the endocytosis of > 30 ligands, including apolipoprotein E (APOE) and amyloid-β (Aβ), thus playing a critical role in the pathogenesis of Alzheimer's disease (AD)." (PMID 36056345, 2022). "These microglia upregulate factors that have been linked to neurotoxicity, including Nox2 and pathways of Alzheimer’s Disease (AD) during the disease progression (MAPT (tau), PSEN2, and APOE genes) whose mutations are directly linked to familial AD." (PMID 36076972, 2022).
Alzheimer disease (continued). "APOE ε4 allele is reported to be associated with hallucinations and Alzheimer’s disease (AD)-pathological protein in parkinsonian syndromes, patients with DLB + APOE ɛ4 showed more pronounced hallucinations in atypical Parkinson’s disease (PD) cohort." (PMID 36123648, 2022). "Evidence has shown positive relationships between anxiety symptoms and specific cortico-subcortical amyloidosis in older adults, patients with Alzheimer's Disease (AD), and APOE ε4 carriers, but evidence regarding panic attacks is scarce." (PMID 35493812, 2022). "In the central nervous system, APOE is primarily expressed in astrocytes, thus the impact of APOE genotype on the pathophysiology of Alzheimer’s disease is likely to involve astrocytic functioning." (PMID 35702728, 2022). "Allele 4 of the apolipoprotein E gene (APOE ε4) and hypertension are considered risk factors for Alzheimer’s Disease (AD)." (PMID 35624902, 2022). "Although multiple sources of data point to a critical role of astrocytes in the pathology of Alzheimer’s disease both independently and modulated by APOE, in vivo studies of astrocytic function in humans are still challenging." (PMID 35702728, 2022). "Nevertheless, the findings draw a remarkable picture on the relationship between ApoE function as a modulator of pathology in Alzheimer’s disease." (PMID 35838824, 2022). "APOE is involved in lipid metabolism and distribution, and, compared to APOE3, APOE4 increases the risk of developing age-related cognitive decline and Alzheimer's disease." (PMID 36353888, 2022). "ApoE-related replacement therapeutics including ApoE-derived peptides have been developed to treat Alzheimer’s Disease." (PMID 36304458, 2022). "The APOE region accounts for much of the measurable genetic contribution to Alzheimer’s disease, with a smaller contribution from other measured polygenic influences." (PMID 35169705, 2022). "For example, APOE × MIND interactions for all-cause dementia and Alzheimer’s dementia are in opposite directions." (PMID 35807939, 2022). "Odds Ratios for developing Alzheimer disease according to ApoE genotypes ε3/ε4 and ε4/ε4 relative to the ε3/ε3 stratified by the rs10423769_A allele and studies." (PMID 35788729, 2022). "Module 1, on the contrary, contained regions largely unaffected by Alzheimer’s disease pathology, and showed very weak correlation between APOE expression and brain glucose metabolism." (PMID 36092303, 2022). "Further study is needed to determine the functional implications of impaired APOE degradation and reduced autophagic flux in Alzheimer's disease and aging." (PMID 34982109, 2022). "Our sensitivity analysis, excluding the APOE region, replicated only the effects for family history of Alzheimer’s disease and some cognitive measures." (PMID 35953482, 2022). "This in vivo “lipid sink” role has been mimicked in transwell co-cultures, where ectopic LDs in hippocampal neurons from ApoE3 or ApoE4 humanized mouse models of Alzheimer’s disease are cleared by astrocytes via ApoE-dependent extracellular lipid transport." (PMID 35493070, 2022). "An example of this is found in the contrasting results for LDL cholesterol and coronary heart disease at the PCSK9 gene region and those for LDL cholesterol and Alzheimer disease at the APOE gene region." (PMID 35452592, 2022). "Clusterin and ApoE limit amyloid retention in Alzheimer’s disease and mitigate cerebral microbleeds." (PMID 36289630, 2022). "Apolipoprotein E (APOE) genotype, especially APOE-ε4, a genetic marker for sporadic CAA, has been used as a genetic risk factor for CAA and Alzheimer disease (AD)." (PMID 36119691, 2022).
Alzheimer disease (continued). "Although the mechanisms of action are still unclear, the ApoE gene is involved in dementia, Alzheimer’s disease (AD), Parkinson’s disease, and cardiovascular disease (ischemic stroke) development." (PMID 35892323, 2022). "In Alzheimer’s disease mouse models, the global m6A level was increased in the hippocampus and the cortex compared to C57BL/6 mice, and the interaction of FTO and APOE contributed to the increase in Alzheimer’s disease risk." (PMID 36407103, 2022). "Apolipoprotein E (APOE), particularly the E4 allele, is a significant risk factor for Alzheimer’s disease but is also a key HDL-associated protein involved in lipid transport in both the periphery and central nervous systems." (PMID 35884800, 2022). "Low levels of plasma apolipoprotein E (apoE) and presence of the APOE ε4 allele are associated with an increased risk of Alzheimer’s disease (AD)." (PMID 36002891, 2022). "In particular, our subjects are significantly younger (mean age = 61.1 years old) and have higher APOE-ɛ4 carriership and family history of Alzheimer’s disease prevalence." (PMID 35702732, 2022). "APOE genotype is a major risk factor for a number of age-related pathologies including CVD and Alzheimer's disease." (PMID 35694676, 2022). "The non-APOE PRS was associated with higher odds of own and family diagnosis of Alzheimer’s disease and lower odds of family history of chronic bronchitis/emphysema." (PMID 35953482, 2022). "The ε4 allele of apolipoprotein E (APOE), APOEε4, has been identified as one of the greatest genetic risk factors for Alzheimer’s disease (AD) and related dementias (ADRDs)." (PMID 35370604, 2022). "The purpose of this study was to examine the levels of cerebrospinal fluid (CSF) apolipoprotein E (apoE) species in Alzheimer’s disease (AD) patients." (PMID 36324176, 2022). "The apolipoprotein E ε4 (APOE ε4) allele and midlife obesity are independent risk factors for Alzheimer’s disease (AD)." (PMID 36504632, 2022). "The ε4 allele of Apolipoprotein E (APOE), which is carried by approximately one out of six individuals, remains the strongest known genetic risk factor for late-onset Alzheimer’s Disease (AD)." (PMID 36195891, 2022). "Applying our method to direct and proxy GWAS data for Alzheimer’s disease we obtain estimates of liability-scale SNP heritability of AD outside of APOE region that are more than double the most recent estimates." (PMID 35658006, 2022). "For Alzheimer disease, there is evidence that African ancestry–specific genetic factors near APOE account for this difference." (PMID 34424302, 2021). "This analysis highlights APOE and leads to the identification of an intron-3 retaining transcript of APOE, the usage of which is correlated with Alzheimer’s disease pathology and APOE-ε4 status." (PMID 33824317, 2021). "Due to the role of apoE in Alzheimer’s disease development and other neurologic diseases, apoE mimetic peptides have also been tested in various neurologic disease animal models and have yielded promising results." (PMID 33800446, 2021). "Here we evaluate the impact of APOE ε4 genotype on initial cognitive symptoms among those with Alzheimer’s disease pathology (ADP) and Lewy-related pathology (LRP)." (PMID 33485373, 2021). "Our live-imaging data provide a basis to understand the reversed risk associations of APOE alleles between AMD and Alzheimer’s disease." (PMID 33822768, 2021). "Recent genetics findings, including that APOE is a risk factor for EOAD, belie the underlying similarities between EOAD and Alzheimer’s disease." (PMID 34220427, 2021). "Among various genetic factors, the apolipoprotein E (APOE) ε4 allele is the most significant one, accounting for about 5% of the variance in lifetime cognitive decline and 4% of the variance in Alzheimer disease (AD)." (PMID 34061824, 2021).